EEF1A1P9 (eukaryotic translation elongation factor 1 alpha 1 pseudogene 9)
Synonyms: formerly EEF1AL7
Gene: Processed pseudogene on chromosome 4 (105,484,698 to 105,486,080, forward strand). Ensembl gene ENSG00000249264.
Diseases named in the same sentence as EEF1A1P9 in open-access papers:
EEF1A1P9 is named in the same sentence as 1 disease in open-access papers, as found by Europe PMC text mining. Sharing a sentence is not in itself a finding about the gene and the disease. The quoted sentences say what the papers report.
glioma (4 papers, 2019 to 2022). A benign or malignant brain and spinal cord tumor that arises from glial cells (astrocytes, oligodendrocytes, ependymal cells). "In our study, we show that EEF1A1P9 has an HR < 1, indicating it is a protective factor in glioma, and higher expression level of EEF1A1P9 is associated with better prognosis." (PMID 31681595, 2019). "In our study, we screened out five pseudogenes (ANXA2P2, EEF1A1P9, FER1L4, HILS1, and RAET1K) that were differentially expressed between LGG and GBM and were associated with the prognosis of glioma patients." (PMID 31681595, 2019). "EEF1A1P9 was a protective factor (HR < 1), and ANXA2P2, FER1L4, HILS1, and RAET1K were defined as risk factors (HR > 1) in glioma." (PMID 31681595, 2019). "In addition, pseudogenes ANXA2P2, EEF1A1P9, FER1L4, HILS1, and RAET1K were found to be significantly correlated with glioma survival." (PMID 33378744, 2020).